SREBF1 (sterol regulatory element binding transcription factor 1)
Diseases named in the same sentence as SREBF1 in open-access papers (continued):
Sharing a sentence is not in itself a finding about the gene and the disease.
schizophrenia (10 papers, 2010 to 2024). A major psychotic disorder characterized by abnormalities in the perception or expression of reality. "The mutation frequencies of INSIG1 and SREBF1 were both lower than 10% in male and female schizophrenia patients." (PMID 38760414, 2024). "Moreover, the trend signal observed in this subset was mainly driven by variants in the well-known schizophrenia-associated genes SREBF1 and SREBF2." (PMID 29720671, 2018). "The association of polymorphisms in the SREBF1 and SREBF2 genes with schizophrenia was first reported in 2010 and has been replicated in three independent samples." (PMID 34575210, 2021). "Since SREBF1 and SREBF2 on chromosome 17p11.2 and 22q13.2 have both been associated with schizophrenia, the GSEA analysis of the PGC2 schizophrenia GWAS data was re-run after exclusion of these genes." (PMID 29720671, 2018). "In conclusion, we have confirmed that non-coding variants linked to the SREBF1 and SREBF2 genes are associated with increased risk of schizophrenia." (PMID 29720671, 2018). "Cognitive measures (Brief Assessment of Cognition in Schizophrenia-BACS adjusted scores) in patients stratified by SREBF-1 genotype." (PMID 30581395, 2018). "It remains to be clarified whether variants in SREBF1 and SREBF2 influence the risk of schizophrenia through effects on lipid biosynthesis and myelination in the brain." (PMID 29720671, 2018). "We found that a subset of lipid-related genes was nominally associated with schizophrenia (p = 0.037), but this signal did not survive multiple testing correction (FWER = 0.16) and was mainly driven by the SREBF1 and SREBF2 genes that have already been linked to schizophrenia." (PMID 29720671, 2018). "Several studies have reported the importance of SREBF1 and SREBF2 factors in the lipid biosynthesis and their possible involvement in antipsychotic drug effects and the genetic variants of SREBF1 and/or SREBF2 could affect schizophrenia susceptibility." (PMID 22348066, 2012). "In particular, the expression levels of the murine orthologs of the two genes RAI1 (GeneID: 10743) and SREBF1 (6720), which were associated with schizophrenia, a phenotype absent from SMS and PTLS patients, show a strong relationship with gene dosage." (PMID 21124890, 2010).
diabetic nephropathy (9 papers, 2014 to 2025). "HIF1A, PPARA, and SREBF1 were key transcriptional factors for the treatment of diabetic nephropathy by EZP and EYP in renal function." (PMID 40417738, 2025).
viral infection (9 papers, 2020 to 2025). "Among the top 10 downregulated genes, SREBF1, FGFR4, CRAT and PXMP4 showed a similar decrease following different viral infections." (PMID 39625479, 2024).
cervical cancer (8 papers, 2011 to 2025). A primary or metastatic malignant neoplasm involving the cervix. "These orthogonal readouts support a model in which IMP3 sustains lipogenic transcription by enhancing SREBF1 mRNA output, thereby promoting lipid accumulation and membrane remodeling in cervical cancer cells." (PMID 41614778, 2025). "To assess the impact of SREBF1 on CCa progression, we observed an upregulation of SREBF1 in CCa tissues compared to normal cervical cancer using the TCGA database and GEO database." (PMID 38250152, 2024).
lung adenocarcinoma (7 papers, 2012 to 2024). A carcinoma that arises from the lung and is characterized by the presence of malignant glandular epithelial cells. "We specifically focused on SREBF1 gene expression and LD status in cancer cells in vitro, and on the SREBF1 gene expression in a tumor and adjacent healthy tissues of lung adenocarcinoma and squamous cell carcinoma patients." (PMID 36139614, 2022).
renal cell carcinoma (7 papers, 2018 to 2025). "A recent study, in contrast, found that TRIM21/Ro52 inhibits the expression of the lipogenic enzyme via the degradation of sterol regulatory element binding transcription factor 1 (SREBF1), attenuating lipogenesis and tumor growth in renal cell carcinoma." (PMID 37993883, 2023). "In renal cell carcinoma, TRIM21 mediates ubiquitination-mediated degradation of sterol regulatory element binding transcription factor 1 (SREBF1) to inhibit the expression of lipogenic enzymes, thereby blocking lipogenesis and tumor development." (PMID 40735642, 2025).
dementia (6 papers, 2020 to 2023). Loss of intellectual abilities interfering with an individual's social and occupational functions. "Genetic variation in the sterol regulatory element-binding transcription factor 1 (SREBF1), known to play a role in lipid and cholesterol metabolism, is associated with increased susceptibility to dementia and AD." (PMID 34720873, 2021).
Nephropathy (6 papers, 2016 to 2025). A nonspecific term referring to disease or damage of the kidneys. "Healthy controls and kidney disease samples showed strong expression of DNL genes, including ACSS2, NR1H3 (liver X receptor α [LXRA]), NR1H4 (farnesoid X receptor [FXR]), SREBF1, SCAP, PLIN2, PLIN5, ACACAB, ATP citrate lyase (ACLY), and FASN in PT cells and some other tubule cells." (PMID 38051585, 2023).
neuroblastoma (6 papers, 2019 to 2025). Neuroblastoma (NB) is the most common solid, extracranial childhood tumor. "It is still unknown that whether the expression of the six genes, AR, SCAP, SREBF1, SREBF2, HMGCR, and CYP17A1 are closely associated with neuroblastoma patient survival." (PMID 34041015, 2021).
renal carcinoma (6 papers, 2021 to 2025). A carcinoma arising from the epithelium of the renal parenchyma or the renal pelvis. "TRIM21, a E3 ligase, interacts with SREBF1 through its SPRY domain and mediates its ubiquitination and degradation via K63 linkage, suppressing lipid metabolism in renal cancer." (PMID 39944823, 2025). "Among the most altered genes, it has been shown that renal cancer progression can be promoted by upregulation of CXCL8, ADAM9, NDRG1, SOD2, SREBF1 and SREBF2 genes." (PMID 35505422, 2022).
Alzheimer disease (5 papers, 2023 to 2025). A progressive, neurodegenerative disease characterized by loss of function and death of nerve cells in several areas of the brain leading to loss of cognitive function such as memory and language. "The three TFs that have the highest cumulative weight in the models of these genes are SREBF1, SREBF2 and ZEB1, themselves associated with neuronal differentiation and neurodegenerative diseases like Alzheimer’s Disease or Huntington’s Disease." (PMID 38632500, 2024).
HCMV infection (5 papers, 2013 to 2024). "Many of these genes induced by SREBF1 have been previously reported to activate lipogenesis during HCMV infection, inducing the expression of multiple proteins involved in sterol synthesis and fatty acid biosynthesis." (PMID 38117060, 2024). "Furthermore, shRNA-mediated targeting of SCAP, a protein important for SREBF1 processing and activation, has been shown to attenuate HCMV infection." (PMID 38117060, 2024).
acute myeloid leukemia (4 papers, 2023 to 2025). Acute myeloid leukemia (AML) is a group of neoplasms arising from precursor cells committed to the myeloid cell-line differentiation. "We first analyzed The Cancer Genome Atlas (TCGA) LAML (acute myeloid leukemia) dataset and found that higher levels of SREBF1 expression correlated with significantly worse patient outcome (p = 0.0007) in acute myeloid leukemia." (PMID 40263296, 2025). "We found that high expression of SREBF1 associated with poor OS in BLCA (p = 0.016), Mesothelioma (MESO) (p = 0.041), Acute Myeloid Leukemia (LAML) (p = 0.011), and patients with high SREBF1 expression in COAD exhibited significantly inferior disease-free survival (DFS) (p = 0.029)." (PMID 40668814, 2025).
depression (4 papers, 2020 to 2022). "Intriguingly, a recent study showed that SREBF1 is associated with multiple subphenotypes of SCZ, such as hyperlocomotor activity in dark, depression-like and aggressive behaviors, and social deficits." (PMID 32425817, 2020). "The common DEGs of depression and NASH have four TFs, i.e., ATF, SRF, SREBF1, SCRT2." (PMID 34833079, 2021).
psoriasis (4 papers, 2024 to 2026). An autoimmune condition characterized by red, well-delineated plaques with silvery scales that are usually on the extensor surfaces and scalp. "Of the 10 most significantly enriched upstream regulators in each comparison, Sterol Regulatory Element Binding Transcription Factor 1 (SREBF1) was predicted to be enriched only in psoriasis lesions, and POU class 2 homeobox 1 (POU2F1) only in PsA lesions." (PMID 37137278, 2024).
squamous cell carcinoma (4 papers, 2022 to 2025). A carcinoma arising from squamous epithelial cells. "For example, SREBF1 is essential for squamous cell carcinoma viability and migration, and its overexpression is associated with poor survival in squamous cell carcinoma patients." (PMID 36467412, 2022). "Sterol regulatory element binding transcription factor 1 (SREBF1, Gene ID: 6720) is essential for squamous cell carcinoma (SCC) viability and migration, and its overexpression is associated with poor survival in SCC patients." (PMID 35783263, 2022). "Squamous cell carcinomas may have SREBF1 as a potential therapeutic target and prognostic marker." (PMID 36467412, 2022). "In addition, Studies have demonstrated that SREBF1 forms a reciprocal regulatory loop with TP63/KLF5 to promote survival and migration in squamous cell carcinoma." (PMID 40668814, 2025). "We found a significant downregulation of SREBF1 in adenocarcinoma (ADC) and although statistically nonsignificant, also a downregulation in squamous cell carcinoma (SQCC)." (PMID 36139614, 2022).
Stroke (4 papers, 2022 to 2024). Sudden impairment of blood flow to a part of the brain due to occlusion or rupture of an artery to the brain. "For ACD‐stroke, we identified 56 variants mapping to 10 genes on chromosomes 17, 8, 11, 15, 4, and 12, most of which are located at the SREBF1/TOM1L2 locus (p < 1e‐10) on chr17." (PMID 39046104, 2024). "We identified a rare missense variant on SREBF1 exome-wide significantly associated with stroke (rs114001633, p.Pro227Leu, p-value = 7.30 × 10-8), which replicated for hemorrhagic stroke in T1D." (PMID 38862513, 2024).
metastatic tumor (3 papers, 2020 to 2025). "This analysis revealed that SREBF1 and GPNMB were downregulated in metastatic tumor fibroblasts compared to their primary tumor counterparts, and HIF1A was downregulated in metastatic tumor cells compared to primary tumor cells." (PMID 40095604, 2025).
pulmonary fibrosis (3 papers, 2014 to 2023). Chronic progressive interstitial lung disorder characterized by the replacement of the lung tissue by connective tissue, leading to progressive dyspnea, respiratory failure, or right heart failure. "miR29 is associated with the pathogenesis of pulmonary fibrosis and regulates pro-inflammatory cytokine secretion by targeting Insig1, Srebf1 and Lpl." (PMID 24806461, 2014).
Sepsis (3 papers, 2024 to 2025). Sepsis is defined as life-threatening organ dysfunction caused by a dysregulated host response to infection. "SREBF1-deficient DCs also exhibited reduced apoptosis during sepsis." (PMID 40524162, 2025). "Although lipid metabolism dysregulation has been implicated in sepsis pathogenesis, how lipid biosynthesis, particularly mediated by sterol regulatory element-binding transcription factor 1 (SREBF1), leads to dendritic cell (DC) immunoparalysis remains unclear." (PMID 40524162, 2025). "Using a murine sepsis model and bone marrow-derived DCs (BMDCs), we demonstrate that upregulation of SREBF1 led to lipid overload, which subsequently induced endoplasmic reticulum (ER) stress." (PMID 40524162, 2025). "Our study identifies SREBF1 as a central regulator of sepsis-induced DC immunoparalysis by coupling lipid metabolic reprogramming to ER stress activation." (PMID 40524162, 2025). "To evaluate the role of SREBF1 in DC apoptosis during sepsis, we examined the expression of apoptosis-related proteins in DCs from WT and cKO mice." (PMID 40524162, 2025). "Together, these findings demonstrate that SREBF1 acts upstream to initiate lipid-driven ER stress and identify it as a selective regulator of metabolic ER stress pathways in sepsis." (PMID 40524162, 2025). "Our study reveals that SREBF1-mediated lipid metabolism reprogramming drives DC dysfunction in sepsis via ER stress." (PMID 40524162, 2025). "Together, these results from both in vivo and in vitro models demonstrate that SREBF1 promotes immunoparalysis of DCs in sepsis." (PMID 40524162, 2025). "In a cecal ligation and puncture-induced sepsis model, we observed increased lipid biosynthesis and significantly elevated SREBF1 expression in spleen DCs." (PMID 40524162, 2025). "Collectively, these results demonstrate that SREBF1 promotes DC apoptosis and sepsis-related mortality by exacerbating lipid-induced ER stress but does not broadly suppress ER stress from unrelated triggers like TM." (PMID 40524162, 2025). "While previous research has linked lipid metabolism to DC activity, our work uniquely identifies SREBF1 as the central transcriptional regulator of this process in the context of sepsis." (PMID 40524162, 2025). "Consistently, PBMCs from sepsis patients exhibited increased mRNA expression of SREBF1, FASN, ACACA, and SCD1, supporting the clinical relevance of lipid biosynthesis activation." (PMID 40524162, 2025). "Our study identifies SREBF1 as a master regulator of DC dysfunction in sepsis by inducing lipid biosynthesis-driven ER stress via the PERK/eIF2α/ATF4/CHOP axis." (PMID 40524162, 2025). "RBP dysfunction disturbs alternative splicing of lipid metabolism genes, such as SREBF1/CerS2, indicating RBPs as possible therapeutic targets for sepsis-induced liver injury." (PMID 38727856, 2024). "Moreover, Srebf1-/- macrophages exhibited enhanced and prolonged inflammatory responses following pro-inflammatory TLR4 stimulation, while Srebf1-/- mice exhibited exaggerated and prolonged inflammation in a sepsis model." (PMID 40539061, 2025). "In this work, SREBF1 knockout alleviated the immune dysfunction and apoptosis of DCs in sepsis." (PMID 40524162, 2025). "We aimed to explore how SREBF1 regulates lipid metabolism in DCs during sepsis." (PMID 40524162, 2025). "Our data indicate that SREBF1 is involved in DC immunoparalysis, thus exacerbating sepsis severity." (PMID 40524162, 2025). "Our findings unveil SREBF1 as a novel therapeutic target to reverse immunosuppression in sepsis." (PMID 40524162, 2025). "However, whether SREBF1 contributes to DC apoptosis during sepsis remains unknown." (PMID 40524162, 2025).
asthma (2 papers, 2021 to 2025). "Many key lncRNAs implicated in ABPA and asthma were identified, respectively, i.e., AL139423.1-201, AC106028.4-201, HNRNPUL1-210, PUF60-218 and SREBF1-208." (PMID 34221710, 2021).
Cognitive impairment (2 papers, 2018 to 2023). Abnormal cognition is characterized by deficits in thinking, reasoning, or remembering. "Secondary aims include the analysis of the association between the cognitive impairment and psychopathological status and, in a subgroup of patients, the evaluation of the effect of SREBF1 rs11868035 genetic polymorphism on both cognitive functioning and MetS." (PMID 30581395, 2018). "Secondary objectives include the analysis of the relationship between the cognitive deficit and psychopathological status and, in a subgroup of patients, the evaluation of the effect of SREBF1 rs11868035 genetic polymorphism on both cognitive functioning and MetS." (PMID 30581395, 2018).
diffuse large B-cell lymphoma (2 papers, 2023 to 2025). "Besides, we explored the connection between SREBF1 expression levels and tumor stages, which led us to discover a significant effect of SREBF1 expression on the stages of the patients with Diffuse Large B-Cell Lymphoma (DLBC), KIRC, and THCA." (PMID 40668814, 2025).
Fanconi anemia (2 papers, 2021 to 2023). Fanconi anemia (FA) is a hereditary DNA repair disorder characterized by progressive pancytopenia with bone marrow failure, variable congenital malformations and predisposition to develop hematological or solid tumors. "In this study, we showed that SREBF1 is associated with the Fanconi anemia pathway, which is associated with an increased risk of HNSC." (PMID 37090107, 2023). "The heat map shows the top 50 genes, and the Kyoto Encyclopedia of Genes and Genomes (KEGG) enrichment analysis revealed that SREBF1 expression was associated with Fanconi anemia pathway, DNA replication, and homologous recombination." (PMID 37090107, 2023).
head and neck squamous cell carcinoma (2 papers, 2023). A squamous cell carcinoma that arises from any of the following anatomic sites: lip and oral cavity, nasal cavity, paranasal sinuses, pharynx, larynx, and salivary glands. "This suggests that SREBF1 may promote the proliferation and migration of head and neck squamous cell carcinoma through STARD4." (PMID 37090107, 2023). "In conclusion, SREBF1 possibly through upregulation of STARD4 and affects immune infiltration to promote proliferation, migration and inhibit apoptosis in head and neck squamous cell carcinoma." (PMID 37090107, 2023).
lymph node metastasis (2 papers, 2021 to 2024). "Immunohistochemistry results further show that high SREBF1 protein expression is associated with lymph node metastasis and poor survival in IMPC patients." (PMID 34799559, 2021). "The expression of SREBF1 and FASN proteins was significantly associated with a higher level of lymph node metastasis in IMPC (SREBF1, R = 0.405, P = 0.000; FASN, R = 0.521, P = 0.000)." (PMID 34799559, 2021). "Concurrently, elevated expression of the sterol regulatory element-binding transcription factor 1 (SREBF1) protein has been correlated with increased lymph node metastasis and diminished survival rates in IMPC patients, underscoring its potential as a diagnostic and therapeutic biomarker." (PMID 39439806, 2024).
medulloblastoma (2 papers, 2012 to 2014). A malignant, invasive embryonal neoplasm arising from the cerebellum. "Nfe2l2 (Nuclear factor erythroid 2-related factor 2) and Pax3 (paired box gene 3) influence Srebf1 expression in mouse liver and human medulloblastoma cell line." (PMID 24806461, 2014). "In the absence of miR-33b expression data, these results implicate the association between down-regulation of SREBF1 (the host gene of miR-33b) and MYC overexpression and poor prognosis in medulloblastoma." (PMID 22887866, 2012). "SREBF1 expression was significantly lower in medulloblastoma tissues compared with that in normal brain (p = 2.2E-16; Student's t-test)." (PMID 22887866, 2012). "We analyzed SREBF1 (SREBF1a and SREBF1c were not distinguishable) and MYC expression in medulloblastoma from four published reports with openly available data on genetic and gene expression profiles, pathway signatures and clinical pathological features." (PMID 22887866, 2012).
Parkinson disease (2 papers, 2020 to 2024). A progressive degenerative disorder of the central nervous system characterized by loss of dopamine producing neurons in the substantia nigra and the presence of Lewy bodies in the substantia nigra and locus coeruleus. "SREBF1 is associated with pathogenic changes in Parkinson’s disease and plays a role in lysosomal cholesterol accumulation, and changes in this biomarker have also been detected in the brains of GD1 model mice after treatment." (PMID 39201273, 2024). "Srebf1 links lipogenesis to mitophagy and sporadic Parkinson’s disease, and knockdown of Srebf1 blocks the translocation of Parkin into mitochondria, thereby decreasing mitophagy." (PMID 31959236, 2020).
Pheochromocytoma and Paraganglioma (2 papers, 2023 to 2025). "Only in GBM and Pheochromocytoma and Paraganglioma (PCPG), adjacent normal tissues have higher expression of SREBF1." (PMID 40668814, 2025).